PYCR1 (pyrroline-5-carboxylate reductase 1)
Description:
Oxidoreductase that catalyzes the last step in proline biosynthesis, which corresponds to the reduction of pyrroline-5-carboxylate to L-proline using NAD(P)H. At physiologic concentrations, has higher specific activity in the presence of NADH. Involved in the cellular response to oxidative stress.
Synonyms: P5C; ARCL2B; ARCL3B; P5CR; PIG45; PP222; PRO3; PYCR
Tractability: Small molecule: a structure with a bound ligand is known; it has a binding pocket of medium quality. PROTAC: ubiquitination databases record sites on it; its protein half-life has been measured; a small molecule that binds it is known.
Target class: Enzyme; Oxidoreductase
Gene: Protein-coding gene on chromosome 17 (81,932,378 to 81,942,412, reverse strand). Ensembl gene ENSG00000183010.
Subcellular location: Mitochondrion
Pathways (Reactome):
Metabolism: Glutamate and glutamine metabolism
Gene Ontology:
Molecular function: identical protein binding; protein binding; pyrroline-5-carboxylate reductase activity
Biological process: cellular response to oxidative stress; L-proline biosynthetic process; negative regulation of oxidative stress-induced neuron intrinsic apoptotic signaling pathway; regulation of mitochondrial membrane potential; L-glutamate catabolic process; L-glutamine catabolic process
Cellular component: mitochondrion; pyrroline-5-carboxylate reductase complex; mitochondrial matrix
Genetic constraint (gnomAD): Loss-of-function variants: 19 observed, 21.98 expected, observed/expected ratio (o/e) 0.86, 90% interval 0.6 to 1.27. The upper end of that interval is the gene's LOEUF score, 1.27, which puts it in group 5 of 6, group 1 being the genes least tolerant of losing a copy. Missense variants: 429 observed, 423.2 expected, observed/expected ratio (o/e) 1.01, 90% interval 0.94 to 1.1. Synonymous variants: 175 observed, 176.95 expected, observed/expected ratio (o/e) 0.99, 90% interval 0.87 to 1.12.
Gene-disease validity (ClinGen):
ClinGen rates the evidence that PYCR1 causes each of these diseases.
autosomal recessive cutis laxa type 2B (autosomal recessive): Definitive.
Homologues: Orthologues: chimpanzee PYCR1 (96% identical), macaque PYCR1 (96% identical), pig PYCR1 (93% identical), dog PYCR1 (90% identical), mouse Pycr1 (88% identical), guinea pig PYCR1 (87% identical), rat Pycr1 (86% identical), zebrafish pycr1a (80% identical), zebrafish pycr1b (79% identical), tropical clawed frog pycr1 (78% identical), rabbit PYCR1 (62% identical), Caenorhabditis elegans pycr-1 (42% identical), and 1 more. Paralogues in human: PYCR2 (85% identical), PYCR3 (38% identical), NOXRED1 (18% identical).
Diseases named in the same sentence as PYCR1 in open-access papers:
PYCR1 is named in the same sentence as 105 diseases in open-access papers, as found by Europe PMC text mining. Sharing a sentence is not in itself a finding about the gene and the disease. The quoted sentences say what the papers report.
breast cancer (46 papers, 2012 to 2025). A primary or metastatic malignant neoplasm involving the breast. "Compared with other breast cancer types, increased expression of PYCR1 was strongly associated with triple negative breast cancer status." (PMID 37845207, 2023). "We found that high levels of PYCR1 were positively associated with advanced clinical stages of breast carcinomas." (PMID 37845207, 2023). "In breast cancer, PYCR1 expression was associated with tumor size, grade, invasiveness and survival." (PMID 35105345, 2022). "A high expression of PYCR1 was also significantly associated with poor prognostic molecular subtypes of breast cancer, which is consistent with our results of downregulated proline levels post operation compared with that of the preoperative period." (PMID 36090329, 2022). "PYCR1 expression has also been significantly associated with breast cancer tumor size, grade, and invasiveness." (PMID 34239351, 2021). "While little is known about this proline form, studies for the close family member PYCR1 have found that higher levels of mRNA were associated with reduced survival from breast cancer patients." (PMID 34611289, 2021). "The human breast cancer-associated gene pyrroline-5-carboxylate reductase (PYCR1) catalyzed the conversion of P5C to proline and its expression was significantly correlated with the invasion and aggressiveness of breast cancer." (PMID 33172086, 2020). "Evaluation of 1,010 treatment‐naïve samples from the TCGA breast cancer provisional dataset showed that high mRNA levels of PYCR1 were also significantly associated with poor progression‐free survival." (PMID 32960509, 2020). "Furthermore, silencing of PYCR1 has been associated with the inhibition of proliferation and invasiveness of breast cancer cell lines via activation of the AKT/ERK signaling pathway." (PMID 34239351, 2021). "Finally, functional analysis in vivo showed that abundance of PYCR1, a mitochondrial metabolic protein, was associated with drug resistance to chemotherapy, thus stressing the role of this protein in breast cancer." (PMID 32960509, 2020). "Another study found that PYCR1 is causally linked to growth of breast cancer." (PMID 23024808, 2012). "According to previous reports, PYCR1, one of the most important enzymes in the process of proline metabolism, is closely associated with tumorigenesis and tumor progression, including prostate cancer, breast cancer, colon cancer, lung cancer, and liver cancer 19-23." (PMID 35371311, 2022). "SIRT3 deacetylated the Lys228 site of pyrroline-5-carboxylate reductase 1 (PYCR1) to regulate the metabolism of proline, which promoted the development of breast cancer." (PMID 40421455, 2025). "For instance, diminishing PYCR1 activity has been found to increase the cytotoxicity of doxorubicin against MCF-7 breast cancer cells." (PMID 38275897, 2024). "For example, PYCR1 is highly expressed in CAFs from patients with breast cancer, and this key enzyme is needed for proline synthesis that supports collagen production." (PMID 37996700, 2024). "In concordance, we find that PYCR1, highly expressed in TNBC tumors and BCSCs, is correlated with poor survival and a higher risk of metastasis and recurrence in breast cancer patients." (PMID 37845207, 2023). "To explore further the downstream targets responsible for the increase in proline-mediated stem-like traits in breast cancer, we performed RNA-seq based transcriptome analysis of PYCR1-knockdown (shP1-1 and shP1-2) versus control (shNC) cells." (PMID 37845207, 2023). "Using both in vitro and in vivo established models, firstly we document that PYCR1-synthesized proline is required for breast cancer stem-like phenotypes." (PMID 37845207, 2023). "Compared with other genes, the mRNA level of PYCR1 was evidently higher in breast cancer cells, especially the TNBC cells." (PMID 37845207, 2023).
breast cancer (continued). "Collectively, our findings unveil that PYCR1-enhanced proline synthesis displays a critical role in maintaining breast cancer stemness." (PMID 37845207, 2023). "PYCR1 is elevated in the stroma and CAFs in breast cancers, and inhibition of PYCR1 reduced collagen synthesis, tumor growth, and metastasis." (PMID 37046596, 2023). "Here, we identify that proline synthetase PYCR1 is critical for breast cancer stemness and tumor growth." (PMID 37845207, 2023). "To evaluate the clinical relevance of PYCR1 in breast cancer patients, we validated the expression of PYCR1 and downstream cGMP-PKG components and predicted their prognosis using The Cancer Genome Atlas (TCGA) database." (PMID 37845207, 2023). "Targeting PYCR1-enhanced proline signaling provides a novel therapeutic approach for targeting aggressive breast cancer undergoing psychological stress." (PMID 37845207, 2023). "More recently, pyrroline-5-carboxylate reductase 1 (PYCR1), a key enzyme in proline biosynthesis, in CAFs was shown to be necessary for collagen production in breast cancer." (PMID 36765684, 2023). "PYCR1 expression and proline metabolism are upregulated in various cancers, especially in invasive and poorly differentiated breast carcinoma." (PMID 37845207, 2023). "Targeting PYCR1 in CAFs in cotransplantation models of breast cancer reduced tumour collagen and was sufficient to reduce tumour growth and metastasis." (PMID 35760868, 2022). "The PYCR1 interference significantly suppressed the breast cancer cell growth and invasion by regulating AKT/ERK signaling pathway." (PMID 35371311, 2022). "PYCR1 inhibition with pargyline lowered intracellular proline level and inhibited cell proliferation of breast cancer cells." (PMID 35731336, 2022). "A previous study, which collected about 2500 cases from 13 independent microarray datasets, found that PYCR1 was overexpressed in breast cancer." (PMID 35371311, 2022). "It was first identified as a PYCR1 inhibitor in 2019 through screening on the breast cancer cell line SUM-159-PT." (PMID 35105345, 2022). "PYCR1 is a key enzyme for proline synthesis and highly expressed in the stroma of breast cancer patients and in CAFs." (PMID 35760868, 2022). "In breast cancer, PYCR1 has been correlated with poor prognosis, and this for both ER + and ER- breast cancers." (PMID 35105345, 2022). "NFLP inhibition was shown to phenocopy the PYCR1 knockdown in breast cancer cells by inhibiting de novo Pro biosynthesis." (PMID 33477430, 2021). "Overexpression of PYCR1 has been reported in many cancers, including non-small cell lung cancer, prostate cancer (PCa), colon cancer, and breast cancer 18-22." (PMID 34239351, 2021). "In vitro study showed that knockdown of PYCR1 diminished the proliferative potential of breast cancer cells proliferation and sensitize the cells for chemotherapeutic drugs." (PMID 34451829, 2021). "TRPM2-AS stimulated proliferation and suppressed apoptosis of breast cancer cells through sponging miR-140-3p to regulate PYCR1." (PMID 33986660, 2021). "In Breast Cancer (BC) tumors, PYCR1 and ALDH18A1 expression levels varies among specific BC subtype." (PMID 32500033, 2020). "This is particularly relevant in metastases, where both PRODH and PYCR1 have been shown to be up-regulated in models of breast cancer metastasis." (PMID 33109600, 2020). "Functional analysis showed that knockdown of PYCR1 reduced invasion and migration capabilities of breast cancer cell lines." (PMID 32960509, 2020). "NFLP was also shown to phenocopy the PYCR1 knockdown in MCF10A H-RASV12 breast cancer cells by inhibiting de novo proline biosynthesis and impairing spheroidal growth." (PMID 33109600, 2020). "NFLP phenocopies the PYCR1 knockdown in breast cancer cells by increasing proline levels and reducing spheroid growth." (PMID 33109600, 2020). "(ix) Data from tumor tissue from patients with breast cancer have been analyzed focusing on P5C reductase (PYCR1)." (PMID 28990419, 2019).
breast cancer (continued). "They showed that PYCR1 was expressed significantly higher in breast cancers with molecular subtypes with poor outcome." (PMID 28990419, 2019). "Silencing of PYCR1 could inhibit cell proliferation, and invasion and enhance the chemosensitivity to doxorubicin in breast cancer cell lines." (PMID 39768999, 2024). "Importantly, breast cancer patients with elevated expression of PYCR1 and cGMP-PKG signatures exhibited significantly poor survival rates." (PMID 37845207, 2023). "Besides, depletion of PYCR1 also repressed the expression of β-adrenergic receptors and G protein in breast cancer cells, which were the canonical downstream pathway components of psychological stress." (PMID 37845207, 2023). "Furthermore, chemotherapy significantly improves survival in early-stage breast cancer patients with low PYCR1." (PMID 37845207, 2023). "Hence, we examined the xenobiotic metabolism-associated genes (PYCR1, KYNU, CFB, HMOX1 and HES6) expressed in both breast cancer cells and in normal mammary epithelial cells." (PMID 37845207, 2023). "Specially, knockdown of PYCR1 inhibits breast cancer cell invasion by blocking MMP9 activity." (PMID 37845207, 2023). "Therefore, we have identified PYCR1 as a candidate target to reduce tumour collagen to oppose breast cancer progression." (PMID 35760868, 2022). "PYCR1 was also significantly more highly expressed in breast cancer." (PMID 35454935, 2022). "Together, these data provide a link between PYCR1 and collagen in CAFs and breast cancer stroma." (PMID 35760868, 2022). "Next, we investigated the role of PYCR1/2 in proline biosynthesis in breast cancer cells." (PMID 36388465, 2022). "To assess whether targeting PYCR1 in CAFs impacts metastasis, we cotransplanted pCAFs shCtl or shPYCR1 with metastatic 4T1 breast cancer cells in NRMI nu/nu mice." (PMID 35760868, 2022). "Thus, it appears that PYCR1 and ProDH/Pox are attractive targets in Pro-starvation therapies of some tumor types such as ccRCC, breast cancer, and HCC." (PMID 33477430, 2021). "Since PYCR1 is overexpressed in breast cancer, prostate cancer, and lung cancer cells, the silencing of PYCR1 expression could represent approach for cancer treatment." (PMID 34769188, 2021). "NFLP phenocopies the PYCR1 knockdown in breast cancer cells." (PMID 33109600, 2020). "In support of this hypothesis, meta‐analysis of 13 pooled microarray datasets showed better survival of stage II breast cancer patients with low PYCR1 expression." (PMID 32960509, 2020). "Pyrroline-5-carboxylate reductase 1 (PYCR1) can promote tumor cell growth in breast cancer." (PMID 31739630, 2019). "Functional genetic screens show that PYCR1 is involved in the growth of mammary tumors." (PMID 23024808, 2012). "Works in the literature and pan-cancer analyses indicate that PYCR1 is commonly upregulated in various cancers, including kidney adenocarcinoma, gastric cancer, lung cancer, pancreatic ductal adenocarcinoma, renal cell carcinoma, breast cancer, and hepatocellular carcinoma." (PMID 39768999, 2024). "For example, RAC3 promotes the growth of breast cancer cells through the p21-activated kinase-dependent pathway, enhances the proliferation of cancer cells in vitro and in vivo, and facilitates proliferation, migration, and invasion of bladder cancer cells through the PYCR1/JAK/STAT axis." (PMID 38987564, 2024). "Indeed, higher PYCR1 mRNA levels were significantly associated with poor survival in patients with breast cancer, regardless of ER status." (PMID 36388465, 2022). "As collagen influences tumour development, we asked whether targeting PYCR1 in CAFs could affect cancer cells, and cocultured cCAFs with a primary line of breast cancer cells either in a three-dimensional (3D) environment, as spheroids, in microfluidic devices, or in two dimensions." (PMID 35760868, 2022). "PYCR1 may be a potential therapeutic target for treating prostate cancer and breast cancer." (PMID 31739630, 2019).
breast cancer (continued). "In the breast cancer cell/breast CAF co-transplantation models, PYCR1 downregulation in CAFs can decrease tumor collagen content and effectively suppress tumor growth and metastasis." (PMID 38910148, 2024). "ECM sclerosis has been shown to promote FERMT2 translocation to mitochondria and its interaction with pyrroline-5-carboxylate reductase 1 (PYCR1), which regulates crosstalk between the tumor and its microenvironment in breast cancer." (PMID 38352691, 2024). "Altogether, these findings suggest that PYCR1-cGMP-PKG axis is a potential biomarker and a therapeutic target for breast cancer, especially TNBC." (PMID 37845207, 2023). "Clinically, PYCR1 and cGMP-PKG signaling components are highly expressed in breast tumor specimens, conferring poor survival in breast cancer patients." (PMID 37845207, 2023). "Proteomic analysis showed that PYCR1, PYCR2 and P5C synthase (P5CS/ALDH18A1) are all elevated in breast cancer patients’ samples." (PMID 37046596, 2023). "RAC3 facilitates proliferation and invasion of bladder cancer cells via PYCR1/JAK/STAT signaling 26, and promotes invasion and metastasis of breast cancer cells through modulating adhesion and matrix degradation." (PMID 37056933, 2023). "As with the shRNA knockdown of the PYCR1 gene, the treatment of MCF10A H-RASV12 breast cancer cells with NFLP increased proline levels and decreased spheroid growth." (PMID 33109600, 2020). "Although previous study has reported that GTP improves the amount of cGMP to activate PKG and the downstream MAPK pathway, contributing to breast cancer stem-like properties, how cGMP-PKG is activated by PYCR1 in BCSC maintenance remains unclear." (PMID 37845207, 2023). "We further explored whether high PYCR1 and COL1A1 expression correlated with clinical outcomes in patients with breast cancer." (PMID 35760868, 2022). "c-Myc has also been positively correlated with PYCR1 expression in luminal B breast cancer, but not in the luminal A subtype, suggesting that the regulation of c-Myc on PYCR1 transcription is dependent on specific tumor types." (PMID 34503295, 2021). "Finally, expression of P5CS, PYCR1/2/L is increased by c-MYC and PI3K signaling in luminal B breast cancer as was previously shown in cultured cancer cells after ectopic expression of c-MYC." (PMID 32500033, 2020). "It was also observed in population studies that chemotherapy significantly improved the survival rate of patients with low PYCR1 expression at the early stage of breast cancer, which confirmed that the lack of PYCR1 might enhance the chemosensitivity of doxorubicin to breast cancer." (PMID 36119513, 2022). "In one prognostic study performed by WGCNA, a significant negative correlation between the high expression of PYCR1 and TRPM2-AS and the breast cancer survival was elucidated." (PMID 31739287, 2019).